RN7SL172P (RNA, 7SL, cytoplasmic 172, pseudogene)
Gene: Miscellaneous RNA gene on chromosome 3 (121,653,994 to 121,654,296, reverse strand). Ensembl gene ENSG00000243544.
Homologues: Orthologues: chimpanzee Metazoa_SRP (99% identical), macaque Metazoa_SRP (93% identical). Paralogues in human: RN7SL1 (81% identical), RN7SL3 (81% identical), RN7SL2 (80% identical), RN7SL732P (80% identical), RN7SL302P (79% identical), RN7SL333P (79% identical), RN7SL113P (78% identical), RN7SL575P (78% identical), RN7SL714P (78% identical), RN7SL414P (78% identical), RN7SL444P (78% identical), RN7SL45P (78% identical), and 701 more.